GALNT3 (polypeptide N-acetylgalactosaminyltransferase 3)
Diseases named in the same sentence as GALNT3 in open-access papers (continued):
Sharing a sentence is not in itself a finding about the gene and the disease.
glioma (3 papers, 2013 to 2022). A benign or malignant brain and spinal cord tumor that arises from glial cells (astrocytes, oligodendrocytes, ependymal cells). "Our study allowed us to identify the four-gene signature (CFH, GALNT3, SMC4, and VAV3) associated with the overall survival of glioma TCGA-LGG patients." (PMID 36539408, 2022). "Treatment with MNF also sensitized C6 glioma tumor xenograft to growth arrest via the downregulation of Galnt3 and other cell cycle regulators, such as Ccna2, Cdkn3, and Bub1b." (PMID 25505565, 2013). "Moreover, comparative analysis of the transcriptome program of the ICD-based DC vaccine with transcriptome data from the TCGA-LGG dataset identified a four-gene signature (CFH, GALNT3, SMC4, VAV3) associated with overall survival of glioma patients." (PMID 36539408, 2022). "The top were GALNT3, ALG6 and B3GNT7, which displayed a p < 1 × 10−9 in the low-grade glioma (LGG) cohort." (PMID 35565254, 2022).
lung adenocarcinoma (3 papers, 2020 to 2025). A carcinoma that arises from the lung and is characterized by the presence of malignant glandular epithelial cells. "In lung adenocarcinoma, high GALNT3 expression correlates with poorer survival outcomes, but also with elevated immune cell infiltration." (PMID 39860532, 2025). "GALNT3 expression was found to be restricted to glandular epithelial cells in lung adenocarcinoma and to be downregulated in mesenchymal like cells in epithelial-mesenchymal transition models." (PMID 32582529, 2020).
iron deficiency (2 papers, 2019 to 2023). "This reduction in GalnT3 mRNA may contribute to an increase in FGF23 cleavage under conditions characterized by elevated erythropoietin, such as iron deficiency anemia, inflammation, or exogenous treatment with synthetic erythropoietin." (PMID 37681408, 2023). "Furin plays an important role in regulation of FGF23 cleavage in iron deficiency and inflammation, whereas under conditions of high EPO GalNT3 inhibition might augment cleavage." (PMID 30971944, 2019).
neuroblastoma (2 papers, 2023 to 2025). Neuroblastoma (NB) is the most common solid, extracranial childhood tumor. "In contrast, our findings in MYCN-amplified neuroblastoma show that GALNT3 is downregulated, which coincides with reduced immune cell infiltration." (PMID 39860532, 2025). "A recent study demonstrated that a signature consisting of five genes (AKR1C2, NCAN, AHCY, FBP2 and GALNT3) has potential prognostic values in neuroblastoma." (PMID 36701414, 2023).
prostate carcinoma (2 papers, 2010 to 2019). A carcinoma that arises from epithelial cells of the prostate gland. "Moreover, increased GALNT3 and GALNTT6 co-expression has been detected in pancreatic and prostate carcinomas, and a strong correlation between both GALNT3 and GALNT6 expression has been reported during the different stages of endometriosis." (PMID 31071912, 2019).
acute pancreatitis (1 paper, 2024). An acute inflammatory process that leads to necrosis of the pancreatic parenchyma. "Further screening identified four genes (ACSL4, GALNT3, WSB1, and IL1R1) that were significantly upregulated in severe acute pancreatitis (SAP) in both human and mouse samples." (PMID 38862656, 2024).
Autoimmunity (1 paper, 2020). The occurrence of an immune reaction against the organism's own cells or tissues. "Nevertheless, the generally low prevalence of autoimmune diagnoses could also result from the CDG represented in our group which lacks (e.g., G6PC3-, SLC37A4- and GALNT3-CDG) more extensive autoimmunity reports." (PMID 32635232, 2020).
cholangiocarcinoma (1 paper, 2022). A carcinoma that arises from the intrahepatic biliary tree (intrahepatic cholangiocarcinoma) or from the junction, or adjacent to the junction, of the right and left hepatic ducts (hilar cholangiocarcinoma). "For example, miR-10b-3p upregulation was shown to enhance HCC progression via suppressing CMTM5 expression, while miR-885-5p was able to target GALNT3 and to thereby inhibit PI3K/AKT/MMP signaling to disrupt intrahepatic cholangiocarcinoma metastasis." (PMID 36217480, 2022).
Globozoospermia (1 paper, 2024). Any structural anomaly of the acrosome resulting in a round sperm head. "Strikingly, Galnt3 knockout mice display globozoospermia and a failure of acrosome formation similar to our Atp6v0a2 mutants." (PMID 39680136, 2024).
hypophosphatemic rickets (1 paper, 2023). Rickets due to low serum phosphate concentrations, the cause of which can be nutritional or genetic. "Consequently, genetic disorders caused by inactivating GalnT3 and Fam20C mutations, such as familial tumoral calcinosis and hypophosphatemic rickets, are unlikely to be influenced by VDR-mediated regulation of FGF23 cleavage." (PMID 37681408, 2023).
influenza (1 paper, 2021). An acute viral infection of the respiratory tract, occurring in isolated cases, in epidemics, or in pandemics; it is caused by serologically different strains of viruses (influenzaviruses) designated A, B, and C, has a 3-day incubation period, and usually lasts for 3 to 10 days. "Of note, GALNT3 levels were correlated with lower IL-6 response upon SARS-CoV-2 stimulation after influenza vaccination, possibly contributing to the beneficial effects of the vaccine." (PMID 34695164, 2021).
pancreatic ductal adenocarcinoma (1 paper, 2019). An infiltrating adenocarcinoma that arises from the epithelial cells of the pancreas. "Knockdown of O-glycosyltransferase GALNT3 resulted in increasing the expression of poorly differentiated pancreatic ductal adenocarcinoma (PDAC) markers and influencing the O-glycans (Tn and T) expression in EGFR and Her2 in PDAC cells." (PMID 31355147, 2019).
Raine syndrome (1 paper, 2021). "This cleavage is further regulated via phosphorylation by FAM20C (family with sequence similarity 20, member C, also known as DMP4; the gene mutated in Raine syndrome) and O-glycosylation by GALNT3 (polypeptide N-acetylgalactosaminyltransferase 3)." (PMID 33815294, 2021).
serous ovarian adenocarcinoma (1 paper, 2014). "Our analyses revealed that GALNT3 expression displayed significant inverse association with PFS of serous ovarian adenocarcinoma patients with advanced disease; i.e., women with lower GALNT3 expression had a better survival without progression than those with higher GALNT3 expression (p=0.034)." (PMID 24504219, 2014).
tumor (27 papers, 2005 to 2025). "Given that GALNT3 KO cells present a decrease in the expression of some fucosylated antigens and that its expression was associated in epithelial cells, we analysed whether it could also contribute to the recognition of tumour cells by DC-SIGN." (PMID 35017635, 2022). "GALNT3, part of the GalNAc transferase (GalNAc-Ts) family, is associated with EMT and variably expressed across different tumor types, implicating it in cancer development." (PMID 41171827, 2025). "Given that GALNT3 has also been found to be expressed in certain immune cells, it is conceivable that the increase in GALNT3 detected in metastatic tumours reflects changes in immune components of the stroma." (PMID 37391533, 2023). "Among tumor suppressor genes in the model, GALNT3 represents polypeptide N-acetylgalactosaminyltransferase 3, participating in the processes of O-linked oligosaccharide biosynthesis and glycoprotein metabolic processes." (PMID 35517412, 2022). "As for mice injected with GALNT3/T6 KO cells, animals presented with tumors arising at the site of injection, as well as tumor formation in the pancreas/omentum and gut mesentary area with normal tissue usually still apparent." (PMID 31071912, 2019). "Consistent with our previous in vitro data, tumor specimens derived from GALNT3 KO and GALNT3/T6 KO cells showed low immunohistochemical (IHC) staining intensity for the GALNT3 protein." (PMID 31071912, 2019). "The five TAAs identified (Tes, Rcn2, Rnf4, Cradd, Galnt3) are those whose expression is linearly related to the tumor mass increase in BALB-neuT mammary glands." (PMID 16351756, 2005). "Recently, loss of GALNT3 in poorly differentiated PDAC was shown to alter glycosylation of Erythroblastic Leukemia Viral Oncogene Homolog (ErbB) family proteins, and further associated with increased tumor aggressiveness." (PMID 32582529, 2020). "This suggests that GALNT3 may influence immune cell dynamics across various tumor types." (PMID 39860532, 2025). "Survival and tumor burden analysis was carried out on seven of eight control mice (one mouse was removed due to bowel obstruction, with no sign of disease), eight of eight GALNT3 KO mice and seven of eight GALNT3/T6 KO mice (one mouse was removed due to infection prior to tumor establishment)." (PMID 31071912, 2019). "Immunohistochemistry (IHC) on clinical tumor samples confirmed that the protein expression levels of MPP5, SNX7, LSM12, and GALNT3 were distinctively predictive for CC patients." (PMID 41171827, 2025). "GALNT3 can glycosylate MUC1, which further activates the PI3K/Akt pathway and promotes tumour proliferation and invasion." (PMID 35610231, 2022). "The effect of single GALNT3 and double GALNT3/T6 inhibition was monitored both in vitro (on EOC cells roliferation, migration, and invasion) and in vivo (on tumor formation and survival of experimental animals)." (PMID 31071912, 2019). "Accordingly, GALNT3/T6 KO-derived tumor tissues showed reduced staining intensity for all of GALNT6, FN1, and MUC1 when compared with the Ctrl and GALNT3 KO tissues." (PMID 31071912, 2019). "The expression of three genes (FAM55C, GALNT3, and DSE) was significantly (p < 0.05) lower in tumor tissues than in normal tissues." (PMID 29848370, 2018). "Alterations in expression levels of genes, such as LOX, ATP5L, GALNT3, and MME revealed by large-scale sequencing were confirmed between cell lines as well as in tumor specimens with different ERBB2 backgrounds." (PMID 21731642, 2011). "Finally, the genes ARID4B, GALNT3, and KPNA6 were identified as other possible candidate tumor biomarkers." (PMID 37761387, 2023). "Finally, we used TIMER database determine the correlations between GALNT3, CYCS, EIF5A, and ITGB4 and six types of tumor-infiltrating immune cells." (PMID 35651789, 2022).
tumor (continued). "Among the GTs highlighted in this process GALNT1, GALNT2 and GALNT3, members of the UDP-N-α-D galactosamine:polypeptide N-acetylgalactosaminyltransferases (GALNT) family, were described to be involved in different biological processes, including tumor progression, proliferation, and migration." (PMID 40096084, 2025).
cancer (15 papers, 2010 to 2025). A tumor composed of atypical neoplastic, often pleomorphic cells that invade other tissues. "Consistent with our observations here, loss of GALNT3 previously has been associated with the mesenchymal phenotype as well as with a poorer cancer prognosis." (PMID 20885998, 2010). "Multiple functional assays were employed to compare cancer-related phenotypic changes acquired in EOC cells upon knocking out one (GALNT3) or two members (GALNT3/T6) of the GalNAc-T family." (PMID 31071912, 2019). "Consecutive canonical and functional pathway and network analyses generated through Ingenuity Pathway Analysis (IPA) software sustained the cancer-related phenotypic changes observed in A2780s cells following single (GALNT3) gene KO and double (GALNT3/T6) gene KO." (PMID 31071912, 2019). "GALNT3 and B3GNT3 have been implicated in the regulation of tumorigenesis in many cancers." (PMID 30466404, 2018). "Next, we decided to verify if shRNA-mediated GALNT3 gene knockdown could produce any cancer-related phenotypic changes in EOC cells." (PMID 24504219, 2014). "Alterations to O-glycan initiation through modulation of the GALNTs, particularly GALNT3, may also affect cancer cell behavior by changing the glycoform of target protein(s) and thereby altering interactions with the cellular environment." (PMID 20885998, 2010). "Regarding initiation of GalNAc-type O-glycosylation, GALNT2, GALNT3, GALNT6, GALNT7, and GALNT14 were highly expressed in both cancer types, LUAD and LUSC." (PMID 40718829, 2025). "Using the Genomics of Drug Sensitivity in Cancer (GDSC) and The Cancer Genome Atlas (TCGA) databases, we identified 4 biomarkers (CYTH3, GALNT3, S100A14, and ERI1) to predict cisplatin sensitivity." (PMID 34676288, 2021). "Our previously published data were also indicative of a possible functional overlap of the GALNT3 and GALNT6 enzymes in cancer." (PMID 31071912, 2019). "Moreover, because downregulation of MUC1 in cancer cells can inhibit cell migration by promoting the expression of the cell adhesion molecules E-cadherin and β-catenin, we also investigated the impact of GALNT3 knockdown on E-cadherin and β-catenin protein expression." (PMID 24504219, 2014). "GALNT3 knockdown was also accompanied with increase of the cell adhesion molecules β-catenin and E-cadherin, which are normally suppressed by MUC1 in cancer, thus supporting the role of the GALNT3-MUC1 axis in EOC invasion." (PMID 24504219, 2014). "Another gene of note is Galnt3 (UDP-GalNAc transferase 3), whose overexpression promotes cancer cell growth through its role in cell cycle regulation." (PMID 25505565, 2013). "We confirmed the absence of GALNT3 in platelets, using western Blot and flow cytometry in comparison with cancer cells." (PMID 40096084, 2025).
genetic disorder (3 papers, 2021 to 2024). "Tumoral calcinosis is an extremely rare genetic disease caused by mutations in three genes, GALNT3, FGF23, and KL, which disrupt phosphorus metabolism." (PMID 38792634, 2024).
adenocarcinoma (2 papers, 2010 to 2014). A common cancer characterized by the presence of malignant glandular cells. "It has been demonstrated that GALNT3 expression is associated with the differentiation or biological behavior of human adenocarcinomas through the initial glycosylation of mucin-type O-linked glycoproteins." (PMID 24504219, 2014). "Notably, GALNT3 expression is restricted to glandular epithelial cells in normal tissue and adenocarcinomas." (PMID 20885998, 2010).
infection (2 papers, 2019 to 2024). The state of being infected such as from the introduction of a foreign agent such as serum, vaccine, antigenic substance or organism. "Early in infection, we observed some differences in the trafficking of EBOV GP—lower and enhanced GP colocalization with lysosomal marker LAMP1 was seen in GALNT2 KO and GALNT3 KO cells, respectively." (PMID 38757972, 2024). "Interestingly, compared with WT, C1GALT1C1 KO- and GALNT3 KO-produced AdV-5 exhibited on average 11.4-fold and 6.5-fold lower titers, respectively, on day 6 post-infection, though not statistically significant." (PMID 38757972, 2024).
GALNT3 also shares sentences with these, for which no sentence is quoted: Hyperphosphatemic familial tumoral calcinosis (6 papers); gastric carcinoma (3); colon carcinoma (2); Infertility (2); osteoporosis (2); amelogenesis imperfecta (1); breast tumor (1); Cerebral ischemia (1); colorectal cancer 1 (1); dental abscesses (1); endometriosis (1); Hypercalcemia (1); hypogonadism (1); hypophosphatemia (1); intervertebral disc degeneration (1); iron deficiency anemia (1); male infertility (1); metabolic disorders (1); normophosphatemic familial tumoral calcinosis (1); oral squamous cell carcinomas (1); serous ovarian tumors (1); skeletal dysplasia (1); type 2 diabetes (1); Wilms tumor (1).